NRG4 (neuregulin 4)
Diseases named in the same sentence as NRG4 in open-access papers (continued):
Sharing a sentence is not in itself a finding about the gene and the disease.
Hepatic steatosis (32 papers, 2016 to 2025). Steatosis is a term used to denote lipid accumulation within hepatocytes. "Aerobic exercise has been shown to alleviate metabolic dysfunction-associated fatty liver disease by upregulating the adipokine Nrg4 and inhibiting hepatic cGAS–STING activation." (PMID 41008530, 2025). "In morbidly obese patients, an increase in circulating Nrg4 levels is associated with the alleviation of hepatic steatosis in the early recovery phase following SG before remarkable weight loss." (PMID 38632600, 2024). "Here, we observed that morbidly obese patients exhibited an increase in circulating Nrg4 levels, which was associated with the amelioration of hepatic steatosis in the early recovery phase following SG before remarkable weight loss." (PMID 38632600, 2024). "Accordingly, these clinical results indicate that the alleviation of hepatic steatosis is strongly associated with the increase in circulating Nrg4 levels in the early recovery phase after bariatric surgery." (PMID 38632600, 2024). "In experimental studies, in neuregulin-4 null mice, an increase in the amount of triglyceride (TG), development of hepatic steatosis and associated liver enzyme elevation were observed." (PMID 37373801, 2023). "Furthermore, the association of plasma Nrg4 with the degree of hepatic steatosis (measured by chemical shift MRI) and systemic inflammatory and metabolic parameters were assessed." (PMID 33989346, 2021). "Notable batokines include fibroblast growth factor 21 (FGF21), which enhances glucose uptake and lipid oxidation, neuregulin 4 (NRG4), which protects against hepatic steatosis, and bone morphogenetic protein 8b (BMP8b), which enhances the thermogenic capacity." (PMID 40699742, 2025). "Accordingly, the alleviation of hepatic steatosis was partly attributed to the upregulation of fatty acid oxidation as well as the downregulation of de novo lipogenesis via Nrg4 after bariatric surgery." (PMID 38632600, 2024). "Due to convincing evidence of a link between an increase in Nrg4 and the alleviation of hepatic steatosis, we questioned how circulating Nrg4 influenced hepatic lipid deposition." (PMID 38632600, 2024). "Taken together, these observations indicate that bariatric surgery, which depends on an increase in the circulating Nrg4 concentration, alleviates hepatic steatosis." (PMID 38632600, 2024). "A case–control study was designed to evaluate the impact of three of the most common adipokines (Nrg4, leptin, and adiponectin) on hepatic steatosis in the early recovery phase following sleeve gastrectomy (SG)." (PMID 38632600, 2024). "We further explored the functional role of circulating Nrg4 in this alleviation of hepatic steatosis after bariatric surgery." (PMID 38632600, 2024). "Increased expression of neurotrophic factors including GDNF, CNTF, BDNF, and NRG4 all alleviate hepatic steatosis." (PMID 32175323, 2020). "Restoration of hepatic c-FLIP expression in HFD-fed NRG4 knockout mice using adenovirus blocked the progression of hepatic steatosis to NASH." (PMID 32175323, 2020). "Collectively, these studies demonstrate that adipose tissue-derived NRG4, via an endocrine fashion, can improve hepatic steatosis, inflammation and fibrosis." (PMID 32175323, 2020). "We also identified hepatic fatty acid β-oxidation and ketogenesis as a new downstream target of Ngr4 in hepatocytes, likely contributing to the protective effects of Nrg4 on hepatic steatosis." (PMID 28752050, 2017). "SRS microscopy revealed that Nrg4 KO mice developed more severe hepatic steatosis following high-fat feeding, as shown by the presence of large lipid droplets in hepatocytes." (PMID 28752050, 2017). "Nrg4 protects mice from diet-induced hepatic steatosis in part through activation of hepatic fatty acid oxidation and ketogenesis." (PMID 28752050, 2017). "Nrg4 gene transfer curbed HFD-induced hepatic steatosis by inhibiting lipogenesis and PPARγ-mediated lipid storage." (PMID 27184920, 2016).
Hepatic steatosis (continued). "Moreover, we observed that hepatic steatosis was much more severe in Nrg4-KO-sham mice than in the other groups (all p values < 0.0001), which indicates that Nrg4 protects against hepatic steatosis, as previously reported." (PMID 38632600, 2024). "Protection from hepatic steatosis was also found in subjects with high neuregulin-4 levels." (PMID 37373801, 2023). "Finally, Nrg4 transgenic mice significantly improved lipid metabolism disorders and hepatic steatosis, supporting the potential therapeutic role of Nrg4 in NAFLD." (PMID 36703934, 2022). "These interesting findings demonstrated that Nrg4 deletion can lead to hepatic steatosis by inducing abnormally increased hepatic lipogenesis and that increased Nrg4 expression may be a therapeutic target for NAFLD." (PMID 36703934, 2022). "However, ultrasonography has poor sensitivity to detect and quantify hepatic steatosis and is therefore suboptimal to investigate the correlation between circulating Nrg4 levels and the presence or degree of hepatic steatosis." (PMID 33989346, 2021). "Hence, we designed a case–control study to evaluate the impact of three of the most common adipokines (Nrg4, leptin, and adiponectin) on alleviating hepatic steatosis during the early recovery phase following sleeve gastrectomy (SG, one of the most popular surgical methods)." (PMID 38632600, 2024). "Secondly, causality between circulating Nrg4 levels and hepatic steatosis or fibrosis development could not be investigated because of the cross-sectional nature of the study." (PMID 33989346, 2021). "When fed a high-fat diet, mice overexpressing Nrg4 specifically in the liver and adipose tissues gained significantly less weight than control mice and exhibited improvements in glucose tolerance, lipid metabolism, and insulin sensitivity, and decreased hepatic steatosis." (PMID 29721105, 2018). "Moreover, whether NRG4 is responsible for the reduced hepatic steatosis and fibrosis of NprcAKO mice is still to be explored." (PMID 28743802, 2017). "For example, the sympathetic nerve fiber modulator neuregulin 4 (NRG4) negatively regulates brown adipocyte differentiation, hepatic steatosis, and hepatic lipogenesis in a cell-autonomous manner." (PMID 35646712, 2022). "Together, we describe a Pr-dependent induction of Nrg4 in BAT and can link this to an improved hepatic steatosis." (PMID 28733671, 2017). "While NRG4 enhanced thermogenic gene expression in brown and inguinal white adipose tissue, it did not improve systemic metabolic parameters or hepatic steatosis." (PMID 40580113, 2025). "In the liver, NRG4 treatment had no impact on hepatic steatosis in LD mice, as assessed by liver weight, triglyceride content, and expression of genes involved in lipogenesis and fatty acid oxidation." (PMID 40580113, 2025). "Nrg4 transgenic mice developed less severe hepatic steatosis than control following high-fat feeding, whereas mice lacking Nrg4 had more pronounced hepatic fat accumulation." (PMID 28752050, 2017). "It is well known that NRG4, secreted in higher amounts by iBAT, inhibits hepatic de novo lipogenesis and expression of genes involved in this process, thus, establishing a crosstalk iBAT-liver that attenuates hepatic steatosis." (PMID 37843714, 2024). "Further work revealed that Nrg4-ADSC could enhance this beneficial effect by reducing liver lipogenesis, whereas ADSC did not demonstrate this effect, suggesting that the mechanism by which Nrg4 improves IR can be achieved in part by limiting liver steatosis." (PMID 36703934, 2022). "Furthermore, plasma Nrg4 levels were not correlated with the degree of hepatic steatosis measured by chemical shift MRI in NAFLD patients." (PMID 33989346, 2021).
metabolic syndrome (31 papers, 2016 to 2025). A cluster of metabolic risk factors for CARDIOVASCULAR DISEASES and TYPE 2 DIABETES MELLITUS. "Some studies demonstrated an inverse association between circulating NRG4 concentration and characteristics of the metabolic syndrome or the presence of non-alcoholic fatty liver disease." (PMID 36187779, 2022). "Although the beneficial effects of Nrg4 on metabolic syndrome have been documented in previous studies, the underlying mechanism has not been fully elucidated." (PMID 36221104, 2022). "Serum NRG4 concentrations are inversely associated with non-alcoholic fatty liver disease, metabolic syndrome and cardiovascular disease in obese humans, while elevated NRG4 is associated with a decreased risk of NAFLD in both children and adults." (PMID 32372975, 2020). "In support of this, plasma Nrg4 levels were inversely associated with the risk for metabolic syndrome in obese Chinese adults." (PMID 28752050, 2017). "Decreased plasma Nrg4 levels, which may be associated with augmented oxidative stress, inflammation, and dyslipidemia, might be involved in the development of MetS in nT2DM patients." (PMID 29721105, 2018). "In addition to animal studies, studies in obese patients have shown that serum Nrg-4 levels are inversely associated with the risk of metabolic syndrome, suggesting that Nrg-4 concentrations may be a protective factor for the development of metabolic syndrome." (PMID 36915073, 2023). "Various studies have identified NRG4 as a likely marker for diagnosing diabetes and metabolic syndrome, demonstrating decreased levels of this adipokine in these conditions." (PMID 40137134, 2025). "Consistently, a cross-sectional study reported significantly lower serum NRG4 levels in patients with metabolic syndrome compared to normal controls." (PMID 39872218, 2024). "In another study conducted on people with metabolic syndrome, a positive correlation was also found between BMI and NRG4 levels." (PMID 39008201, 2024). "Some studies have found that the level of circulating NRG4 in patients with metabolic syndrome is lower than that in the healthy control group, and the concentration of NRG4 is negatively correlated with the risk of developing metabolic syndrome, and NRG4 concentration may be a protective factor." (PMID 36983737, 2023). "Neuregulin 4 is decreased in obese individuals with metabolic syndrome (MUO-like phenotype) and negatively correlated with waist circumference, body AT percentage, BMI, LDL cholesterol, and fasting glucose concentration." (PMID 38136166, 2023). "It led us to think that serum NRG4 concentrations might be a protective factor in the development of metabolic syndrome." (PMID 39280566, 2024). "The potential application of NRG4 in the intervention of metabolic syndrome is worth expecting." (PMID 39872218, 2024). "On the other hand, in different studies examining neuregulin-4 in metabolic syndrome and non-alcoholic fatty liver disease, it has been shown that there is a negative correlation between neuregulin-4, fasting glucose and TG and a positive correlation with HDL cholesterol." (PMID 37373801, 2023). "Adiposity and adipokines are associated with metabolic disorders, but little is known regarding that whether adiposity measurements link metabolic syndrome (MetS) through circulating neuregulin 4 (Nrg4) and adipsin levels." (PMID 34017266, 2021). "Therefore, more powerful original research with new and realistic markers of metabolic syndrome are warranted to elucidate the exact role of circulating Nrg4 in the development of DM in larger samples and in other ethnic groups." (PMID 31815951, 2019). "However, information about the link between Nrg4 and metabolic syndrome (MetS) is scarce, especially in patients with newly diagnosed type 2 diabetes mellitus (nT2DM)." (PMID 29721105, 2018).
metabolic syndrome (continued). "Other cumulative evidence showed that low Nrg4 levels were associated with increased carotid intimal thickness, severity of CAD, and ACS, advocating that Nrg4 may serve as the link between metabolic syndrome and atherosclerosis." (PMID 39162358, 2024). "Furthermore, neither renal nor metabolic syndrome markers was related to Nrg4, and HbA1c and BMI were positively associated with circulating Nrg4." (PMID 31815951, 2019). "However, information is not available regarding the association between circulating Nrg4 and risk of metabolic syndrome (MetS) in humans." (PMID 27772531, 2016). "Moreover, neuregulin-4 (Nrg4) has been shown to be strongly correlated with metabolic disorders (e.g., MASLD, metabolic syndrome)." (PMID 38632600, 2024). "Consistent with findings in rodents, decreased Nrg4 circulating levels were observed in individuals with T2DM, gestational diabetes, metabolic syndrome, and CAD, suggesting a protective role of Nrg4 against the development or progression of these metabolic and cardiovascular conditions." (PMID 39335642, 2024). "In some studies, significantly lower levels of NRG4 were found in obese individuals with metabolic syndrome compared to those without metabolic syndrome." (PMID 39008201, 2024). "None of the renal function and metabolic syndrome markers were correlated with circulating Nrg4, whereas the HbA1c and BMI were positively correlated (rs = 0.09, 95%CI = 0.03 to 0.16, P = 0.005; rs = 0.20, 95%CI = 0.07 to 0.34, P = 0.003; respectively)." (PMID 31815951, 2019). "The indices of the renal function and metabolic syndrome were not correlated with circulating Nrg4 levels in diabetes patients." (PMID 31815951, 2019). "Nrg4, a novel adipocytokine, has negative correlations with indicators of metabolic syndrome." (PMID 32242042, 2020).
type 2 diabetes (23 papers, 2016 to 2025). "In line with the current study, increased levels of serum NRG4 in insulin resistance-associated diseases, such as type 2 diabetes and polycystic ovary syndrome have been reported." (PMID 36187779, 2022). "In contrast, a recent study described low levels of NRG4 in patients with type 2 diabetes in association to microalbuminuria, suggesting NRG4 as a putative marker of microvascular dysfunction." (PMID 36187779, 2022). "Lower serum levels of Nrg4 may be associated with peripheral neuropathy in patients with newly diagnosed type 2 diabetes." (PMID 40137134, 2025). "This study provides new data on the relationship between the levels of DEFA1, progranulin, and NRG4 and the presence of autonomic neuropathy in patients with type 2 diabetes." (PMID 40137134, 2025). "Circulating Nrg4 levels were measured with an ELISA kit in 164 newly diagnosed type 2 diabetes mellitus (nT2DM) patients." (PMID 32477429, 2020). "NRG4 levels are inversely associated with nonalcoholic fatty liver disease (NAFLD) and type 2 diabetes in rodents." (PMID 31208019, 2019). "Previous reports showed that the presence of type 2 diabetes may influence the level of circulating NRG4 levels." (PMID 33989346, 2021). "Moreover, studies comparing a cohort of body mass index-matched individuals reveals that NRG-4 mRNA levels in WAT are lower in those individuals with impaired glucose tolerance or type 2 diabetes than in those with normal glucose tolerance." (PMID 32655416, 2020). "Biologic therapeutics based on Nrg4 may improve both type 2 diabetes and non-alcoholic fatty liver disease (NAFLD) in patients." (PMID 28752050, 2017). "Given the pleiotropic metabolic benefits elicited by Nrg4, biologic therapeutics targeting this pathway may provide an effective treatment that simultaneously targets type 2 diabetes and NAFLD in patients." (PMID 28752050, 2017). "This study aims to explore the association between serum Asprosin, Nrg-4 level and coronary heart disease(CHD) in patients with type 2 diabetes mellitus(T2DM) and the diagnostic value." (PMID 36915073, 2023). "Furthermore, Nrg4 mRNA expression levels are lower in patients with impaired glucose tolerance or type 2 diabetes than those with normal glucose tolerance, suggesting that Nrg4 may have positive effects on glucose and lipid metabolism." (PMID 35197860, 2021). "Non-alcoholic fatty liver disease (NAFLD) and type 2 diabetes mellitus (T2DM) may result from impaired NRG4 signaling." (PMID 38051471, 2024). "We further detected a significant positive correlation between NRG4 and HDL cholesterol serum concentrations and a negative association with triglycerides, consistent with findings in newly diagnosed type 2 diabetes." (PMID 40580113, 2025). "Nrg4 is shown to protect against type 2 diabetes mellitus and non-alcoholic fatty liver disease because Nrg4 can positively regulate ErbB3 and ErbB4 signaling in hepatocytes and inhibit LXR and SREBP1c, promoting lipogenesis." (PMID 39220365, 2024). "Consistent with our findings, a positive correlation between neuregulin-4, fasting glucose and TG, and a negative correlation with HDL cholesterol have been reported in type 2 diabetes, highlighting the increase of neuregulin-4 in the presence of impaired metabolic control." (PMID 37373801, 2023).
non-alcoholic fatty liver disease (18 papers, 2016 to 2025). "NRG4 increases hepatic fatty acid oxidation, inhibits de novo lipogenesis, and, therefore, potentially protects from nonalcoholic fatty liver disease (NAFLD)." (PMID 38610736, 2024). "They demonstrate that NRG4 derived from brown fat represses hepatic lipogenesis through the signaling of human epidermal growth factor receptor 3 (ErbB3, HER3) and ErbB4 (HER4), ultimately leading to the inhibition of nonalcoholic fatty liver disease (NAFLD)." (PMID 39872218, 2024). "Many NRG4 studies have been conducted in patients with non-alcoholic fatty liver disease and metabolic disease rather than in those with cancer." (PMID 37174100, 2023).